MUC2 (mucin 2, oligomeric mucus/gel-forming)
Diseases named in the same sentence as MUC2 in open-access papers (continued):
Sharing a sentence is not in itself a finding about the gene and the disease.
colitis (continued). "Moreover, mice with a B3galt5 missense mutation, which was observed in IBD patients, showed mild spontaneous colitis because of the reduced sialylation of Muc2, similar to St6galnac6-deficient mice." (PMID 39589551, 2024). "Muc2 is essential for colon protection, and Muc2-deficient mice spontaneously develop colitis." (PMID 37111049, 2023). "Moreover, previous studies showed spontaneous development of colitis in MUC2-deficient mice, which is in line with our findings." (PMID 36614212, 2023). "The deficiency of Muc2 can accelerate the process of colitis." (PMID 35681301, 2022). "AB-PAS staining and immunohistochemical staining of Muc2 mucin were used to detect the effect of Cldn7 deficiency on the mucus layer of mice with colitis, and fluorescence in situ hybridization was used to detect how Cldn7 promotes spatial separation of the gut microbiota from the host." (PMID 35039003, 2022). "To assess whether IL-20 activates ERK1/2 in colitis, we utilized the Winnie mouse model of colitis, which carries a missense Muc2 gene mutation which results in an epithelial cell defect." (PMID 36613621, 2022). "Furthermore, Muc2 deficiency causes spontaneous colitis, and the endogenous IAP level is lower in IBD." (PMID 36421992, 2022). "In addition, deficiency in Muc2 expression leads to spontaneous development of colitis in mice, and diminished mucus production has been observed in IBD patients." (PMID 35529468, 2022). "Missense mutation of Muc2 in Winnie mice results in abnormal Muc2 synthesis, depletion of the mucus layer, and spontaneous development of moderate colitis with epithelial erosions and immune cell infiltration, which closely mimics the condition of patients with UC." (PMID 35791076, 2022). "The role of Muc2 seems to be crucial in intestinal inflammatory disorders, as Muc2-deficient mice show epithelial cell structure deformation, leading to increased inflammatory cell infiltration and developing spontaneous colitis." (PMID 36010681, 2022). "The destruction of this mechanism might explain why the mucous layers of TLR5-/- and epithelial MUC2-deficient mice are more colonized by symbiotic microorganisms, resulting in the eventual development of spontaneous colitis." (PMID 35571126, 2022). "In agreement, mucin-2 (Muc2)-deficient mice show spontaneous colitis." (PMID 34581755, 2021). "Muc2 is critical for maintaining the mucosal barrier as the first physical barrier, and the loss of the Muc2 gene in mice results in the spontaneous development of colitis." (PMID 34804049, 2021). "muc2 deficiency directly results in the development of colitis in mice." (PMID 34759916, 2021). "MUC2 mucin was shown to be involved in the maintenance of a healthy microbiota, with transplantation of Muc2−/− microbiota making Muc2+/+ mice more susceptible to dextran sodium sulfate colitis." (PMID 33502317, 2021). "In patients with UC, a precancerous lesion of colon cancer, the expression of MUC2 was decreased, while in MUC2–/– mice, the early phase of spontaneous colitis was caused by a defective mucus barrier and subsequent contact of bacteria with the intestinal epithelium." (PMID 32695780, 2020). "Moreover, MUC-2 knockout mice develop spontaneous colitis and are more susceptible to haptenization-induced intestinal inflammation." (PMID 32824269, 2020). "The spontaneous and DSS-induced colitis shown in Fam3D−/− mice bears similarities to those reported in O-glycans, Muc2, Cramp, and T-bet-deficient mice, which all showed dysbiosis in association with aberrant inflammatory responses culminating in increased carcinogenesis." (PMID 33219235, 2020). "Muc2 is the gene encoding a primary component of mucus, and Muc2-deficient mice develop colitis." (PMID 32641600, 2020). "In this study, we examine whether voluntary wheel running is protective against primary disease symptoms in a mucin 2-deficient (Muc2−/−) lifelong model of murine colitis." (PMID 33024049, 2020).
colitis (continued). "Nr2f6-deficient mice were highly susceptible to DSS-induced colitis characterised by enhanced weight loss, increased colonic tissue destruction and immune cell infiltration together with enhanced intestinal permeability and reduced Muc2 expression." (PMID 28779026, 2018). "Our previous studies have reported that genetic deletion of Muc2 gene spontaneously causes colitis before three months of age and then progresses to CRC, which was linked to the activation of inflammatory signaling and epigenetic alterations, such as differential expression of microRNAs." (PMID 30231491, 2018). "In the present study we aimed to characterize the effects of QBECO treatment on gastrointestinal pathology using two different experimental models of colitis, the commonly used DSS model of chemical-induced colitis and the spontaneous colitis that develops in Muc2 deficient (Muc2−/−) mice." (PMID 30319652, 2018). "In conclusion, there were significant differences of gut microbiota between Muc2−/− and Muc2+/+ mice, and the dynamic changes of microbiota might contribute to the development of colitis and colitis-associated colorectal carcinogenesis." (PMID 30231491, 2018). "Muc2 knockout mice are more susceptible to DSS-induced colitis." (PMID 30002285, 2018). "MUC2 is critical for colon protection, as Muc-2 deficient mice spontaneously develop colitis." (PMID 27149619, 2016). "Hence, the discovery that VIPKO mice possessed significantly fewer morphologically mature goblet cells, and produced less Muc2 and Tff3 than WT mice offers an additional explanation for their susceptibility to chemically induced colitis." (PMID 25932952, 2015). "Spontaneous colitis and colitis-associated colon cancer resulted from Muc2 knock-out in mice." (PMID 25755668, 2015). "It is reported that Muc2 helps the disassociation of pathogenic and normal microbiota from the intestinal mucosa, and thus prevents infectious colitis, and Muc2-deficient mice develop spontaneous colitis." (PMID 26217323, 2015). "Of interest, we have recently demonstrated that constitutive claudin-1 expression induces Notch signaling which in turn suppresses goblet cell differentiation and muc-2 expression to compromise the mucus barrier and thus increase susceptibility to colitis in Cld-1Tg mice." (PMID 24997475, 2014). "Similarly, Agr2-deficient mice were highly susceptible to DSS-induced colitis due to abnormalities in MUC2 synthesis." (PMID 22514630, 2012). "Furthermore, missense mutations in the Muc2 gene results in aberrant Muc2 oligomerization, leading to endoplasmic reticulum stress and subsequently increased susceptibility to colitis." (PMID 20138044, 2010). "Moreover, our study also demonstrated that EcNP3 could improve the loss of goblet cells and the production of MUC‐2 in DSS‐induced colitis mice." (PMID 39553425, 2024). "Similarly, MUC2 knockout mice are more susceptible to the development of colitis." (PMID 38612988, 2024). "Notably, studies revealed the indispensable nature of the SUML in gut health, as mice deficient in mucin 2 (MUC2), a glycoprotein constituting the majority of the mucus, exhibited spontaneous colitis, resembling the presentation seen in dextran sulfate-sodium–induced colitis." (PMID 38321650, 2024). "Indeed, in mice deficient in MUC2, the main component of intestinal mucus, a normal mucus layer is not formed, leading to intestinal bacteria invasion into the colonic mucosa and subsequent spontaneous onset of colitis." (PMID 39589551, 2024). "RELMβ expression in Muc2-deficient mice significantly stimulates secretion of the antimicrobial lectin RegIIIβ that exerts its microbicidal effect predominantly on Gram-positive Lactobacillus species, which leads to microbial dysbiosis that exacerbates colitis." (PMID 36691020, 2023). "Moreover, muc2-deficient mice, in which the mucus layer is defective, develop spontaneous colitis." (PMID 36375841, 2023).
colitis (continued). "However, MT supplementation significantly suppressed A. veronii colonization-induced proliferation of Aeromonas and LPS, restored MUC2 deficiency, and improved colitis, which strongly indicated that Aeromonas coupling with goblet cells promoted MUC2 depletion, further inducing colitis." (PMID 35355860, 2022). "Notably, Muc2 deficiency causes spontaneous colitis in mice." (PMID 34911745, 2021). "However, the inability of the Muc2 deficient mice to flush away C. rodentium may also be due to an impaired ion secretory response as a result of the more severe colitis, damaged epithelium, and increased bacterial density in these mice." (PMID 24386378, 2013). "As a manifestation of colitis induction, Ki67+ proliferating cells and MUC2+ goblet cells decreased after 5 days of treatment, as expected." (PMID 41459492, 2025). "V9 was found to promote the recovery of the number of cuprocytes in colitis mice by H&E staining, and promote the secretion of the mucin MUC2, one of the most prominent components of the intestinal mucus barrier." (PMID 39926427, 2025). "In our study, restoring GLP-1 signaling during colitis in FDD mice significantly up-regulated mucus-related genes (e.g. Muc2 and Tff3), underscoring its role in goblet cell function." (PMID 41202140, 2025). "N-glycosylation proceeds via the OST–ER trimming–Golgi extension cascade; tunicamycin blockade of N-glycan transfer slows MUC2 dimer/assembly and impairs secretion, and misfolded Muc2 in Winnie/Eeyore models links folding defects to spontaneous colitis." (PMID 41301470, 2025). "Concurrently, ELISA results also indicated that quercetin administration led to a substantial 44.1 % increase in colonic MUC2 protein levels in colitis mice." (PMID 40909112, 2025). "Animal studies have demonstrated that L-fucose supplementation (aimed at increasing MUC2 terminal fucosylation) can significantly alleviate experimental colitis in mice." (PMID 41301470, 2025). "The UAF1 inhibitor effectively restored alcian blue staining and goblet cells, while elevated Muc-2 level in the colon tissue of colitis mice (P < 0.05 and P < 0.01)." (PMID 39966502, 2025). "This is illustrated by the spontaneous development of colitis in mice invalidated for Muc-2, the main mucin expressed in the intestine." (PMID 40723233, 2025). "Previous reports have shown that kombucha supplementation improves the mRNA expression of MUC2, occludin, claudin‐1, ZO‐1, and ZO‐2 in mice models of colitis and type 2 diabetes." (PMID 40822525, 2025). "Consistent with the animal results, B3GNT7 and MUC2 expression was significantly lower, and the expression level of FUTs was unchanged in human colitis." (PMID 38979515, 2024). "Studies have shown that MUC2 deficiency exacerbates colon inflammatory responses and spontaneous colitis occurs in MUC2 knockout mice." (PMID 38243258, 2024). "For example, Painong San, a Chinese herbal compound for the treatment of colitis, increased the expression of MUC2 protein in the colon, and P. lactiflora downregulated the expression level of AQP3 in the colon of constipated rats." (PMID 38634140, 2024). "Meanwhile, colonic TJ proteins ZO-1, MUC2, claudin-1, and occludin in colitis mice pre-treated with B. tequilensis YB-2 significantly increased their expression levels and played a critical part in maintaining the epithelial barriers of the mouse colon." (PMID 38998101, 2024). "Murine deletion of Muc2 results in bacterial contact with the colonic epithelium, infection, development and exacerbation of colitis, as well as onset of colorectal cancer." (PMID 38474346, 2024). "A comprehensive proteomic pipeline using data-independent acquisition was applied to decellularized colon samples from the Muc2 knockout (Muc2KO) mouse model of colitis for an in-depth characterization of extracellular matrix remodeling." (PMID 38199279, 2024).
colitis (continued). "The mRNA expression of ZO-1, Cldn4 and Cldn8 was significantly increased while the Muc2 mRNA expression was significantly decreased in the IAP-treated forced-exercise TNBS colitis rats fed an SD (p < 0.05)." (PMID 38255781, 2024). "In our experimental conditions, GILZp, by dampening IL-1α and TNFβ levels and increasing MUC2 transcription, improved the symptoms of colitis, thus helping resolve inflammation and probably stimulating mucus production." (PMID 39456254, 2024). "Intriguingly, ESM significantly enhanced Muc2 expression in the mucus layer, a finding echoed in a mouse colitis model." (PMID 39519252, 2024). "A significant increase in mRNA expression for ZO-1 and Cldn8 and significant decrease in the expression of Cldn4 and Muc2 mRNAs were observed in the group of obese animals with colitis forced to participate in treadmill exercise (p < 0.05)." (PMID 38255781, 2024). "Using in vivo and in vitro approaches with WT and conditional AhR KO mice under colitis conditions, AhR was shown to affect production of Muc2 after stimulation with an AhR ligand (I3C), and this appeared to be independent of IL-22." (PMID 38397081, 2024). "Bifidobacterium breve UCC2003 was shown to increase and mucus layer generation genes including Muc2, Muc6, Muc5c, and Muc4 and Gja1 and Gjb8 in the mucosa-associated with DSS colitis." (PMID 39849930, 2024). "Studies in animal experimental models of colitis have also found that whey protein and soy protein as dietary protein sources can increase the secretion of colonic MUC2 to reduce intestinal mucosal damage." (PMID 39064745, 2024). "In DSS-induced colitis, MUC1 expression is increased and Muc1−/− mice have lower colitis severity accompanied by an increase in expression of MUC2 and MUC3 in a compensatory manner." (PMID 38612988, 2024). "This is consistent with observations that mice deficient in Mucin 2 (MUC2), the main component of colonic mucus in humans and mice, develop spontaneous colitis and premature death upon infectious colitis." (PMID 38521185, 2024). "The current study’s findings suggest that AhR plays an important role in regulating mucin synthesis by goblet cells, notably Muc2, in both steady-state and colitis conditions." (PMID 38397081, 2024). "In an acute colitis mouse model, a prophylactic MFGM treatment followed by DSS increased the gene expression of Muc2 and Muc4, which was associated with the enrichment of nine genera, including Bifidobacterium." (PMID 38612988, 2024). "In relation to barrier defense, Muc2 is the dominant secreted gel-forming mucin secreted by goblet cells to form the outer mucus layer, and Muc2 knockout mice gradually develop colitis by six months of age." (PMID 38474847, 2024). "In Muc2-/-, Fcgbp mRNA expression was below basal levels during acute colitis and in restitution that healed slower than the Muc2+/+ littermates." (PMID 37359538, 2023). "These low-grade enteric inflammations cause mucosal layer damage, especially goblet cell dysfunction through mucin 2 (MUC2) misfolding, ultimately leading to colitis." (PMID 37569708, 2023). "To further explore the protective effects of ω3 OXLP from HM sEVs in experimental colitis, we investigated the expression of mucin-2 (MUC2) by immunofluorescence." (PMID 38054009, 2023). "In our previous study, NLRP6 was found to be involved in the process of 2′-FL alleviating DSS-induced colitis and promoting MUC2 expression in C57BL/6J mice." (PMID 36613400, 2023). "A study has shown that Atractylenolide-1 was able to improve mucoprotein MUC2 and enhance the expression of tight junction proteins ZO-1 and Occludin in mice with colitis." (PMID 37237988, 2023). "attenuates spontaneous colitis in concert with increased production of short-chain fatty acids in Muc2−/− mice." (PMID 36691020, 2023). "The importance of MUC2 for intestinal defense is confirmed with MUC2 knockout murine models that develop spontaneous colitis." (PMID 37317221, 2023).
colitis (continued). "As a result, similar to this experiment, colitis was alleviated by increasing Muc-2 expression in intestinal goblet cells." (PMID 37095161, 2023). "B. pseudocatenulatum treatment improved DSS-induced colitis symptoms and maintained intestinal barrier integrity by up-regulating MUC2 and tight junctions’ expression." (PMID 38068850, 2023). "Yet, the administration of melatonin was found to promote the induction of MUC2-secreting goblet cells via TLR4 stimulation in a DSS-induced model of colitis." (PMID 36768553, 2023). "NLRP6 is reported to regulate MUC2 secretion in goblet cells and its crucial role was demonstrated in a previous study via the enhancement of MUC2 expression in a mouse colitis model." (PMID 36613400, 2023). "Muc2-deficient mice have an impaired mucus layer and are highly susceptible to spontaneous and chemically induced (i.e., DSS) colitis." (PMID 36413219, 2023). "Among the mucins constituting the mucus layer that acts as a barrier against harmful substances in the intestine, the recovery of the expression level of MUC2, which forms a gel only in the colon, is an indicator of improvement in colitis." (PMID 38138587, 2023). "In colonic inflammation, the epithelial cell alteration and goblet cell differentiation result in goblet cell depletion and Muc2 synthesis reductions." (PMID 36986258, 2023). "P. freudenreichii KCTC 1063 isolated from Swiss type cheese protected rats from DSS-induced colitis by stimulating the expression of MUC2 or mucin 2, a glycoprotein that forms an insoluble mucous barrier on the gut epithelium, in intestinal goblet cells." (PMID 37512959, 2023). "In clinical and animal experiments, a thinner mucus layer and lower level of glycosylation of MUC2 have been found in colitis cases, which likely contribute to reduce commensal fitness and drive the microbial dysbiosis in colitis." (PMID 35252301, 2022). "Mice deficient in Claudin 7, hepatocyte nuclear factor 4 alpha (Hnf4a), and Muc2 develop spontaneous colitis." (PMID 35602503, 2022). "HA intervention effectively relieved the dextran sulfate sodium salt (DSS)-induced colitis, reduced inflammation, and enhanced mucosal barrier function, as evidenced by an increment of goblet cell numbers and MUC2." (PMID 36558542, 2022). "A reduced expression of muc2 has also been reported in colitis mice, while in contrast, an increased expression of muc5ac was observed in murine colitis." (PMID 35911682, 2022). "It seems that boosting LPS activates the TLR4-MyD88-GSK-3β-NF-κB pathway and promotes MUC2 depletion, further inducing colitis." (PMID 35355860, 2022). "Our study showed that SD induced colitis, with upregulation of Aeromonas and LPS levels and reductions in goblet cells number and MUC2 protein." (PMID 35355860, 2022). "It is reported that Shaoyao decoction enhanced the Muc2 levels in the colon of the DSS-induced colitis model, and Angelica sinensis protected H9C2 cells against ER stress by activating the ATF6 pathway." (PMID 36010498, 2022). "2′-fucosyllactose (2′-FL) acts as a suppressor of inflammation in DSS-induced colitis, by which regulating gut microbiota composition, improving the recovery of goblet cells and MUC2 secretion, and subsequently affect the TLR4-related inflammatory pathway." (PMID 35252301, 2022). "The results indicated that A. veronii-colonized mice exhibited a colitis phenotype, including an upregulation of Aeromonas and its cell wall composition LPS levels and a downregulation of goblet cells' number and MUC2 protein level." (PMID 35355860, 2022). "Thus ERS-induced mucin depletion seems to be a relevant pathogenetic mechanism of colitis in IL-10 deficient mice; our results demonstrating a significantly reduced number of goblet cells and expression of MUC-2, IL-18, WFDC2 and Xbp-1 in IL-10 deficient mice at young ages support this hypothesis." (PMID 36699599, 2022).